IL22 (interleukin 22)
Diseases named in the same sentence as IL22 in open-access papers (continued):
Sharing a sentence is not in itself a finding about the gene and the disease.
infection (continued). "Moreover, infection with C. rodentium induced significant higher frequencies of IL-22- and IL-17-secreting ILC3 in both WT and CD11c-MyDON mice as compared to MyDOFF or LysM-MyDON mice." (PMID 28520792, 2017). "Initial work in SIV-infected rhesus macaques by our group and others showed that ILC3 are generally restricted to mucosal tissue, express high levels of RORγt, and produce IL-17 and IL-22 much like their human counterparts, but they are depleted or otherwise dysfunctional in infection." (PMID 29326704, 2017). "In addition, ILC3‐derived IL‐22 is essential to prevent bacterial translocation and infections with opportunistic pathogens present in the commensal flora." (PMID 27935637, 2017). "Furthermore, NK cells produce IL-22, a cytokine that has been shown to have a protective role during chronic stages of infection by emergent hyper-virulent strains of Mtb." (PMID 28855906, 2017). "Another new observation was the induction of IL-22 production in milk by the infection." (PMID 28611405, 2017). "Thus, the activity of IL-22 on the epithelium is crucial for protecting the intestinal barrier integrity during infection and supporting the induction of tissue repair and regeneration." (PMID 28520792, 2017). "Since data from our virus-infection model show that IL-22 may influence the lymphoid pools via IL-22R-expressing stromal or epithelial cells, the effects of IL-22 on viral replication may depend on an inflammatory immune environment." (PMID 28634408, 2017). "PAO1 infection induces a tremendous and transient IL-22 mRNA increase at 6 hours of infection." (PMID 28887540, 2017). "In fact we can hypothesize that the reduction of IL-22 levels with the progression of NYHA class can be responsible of the impaired ability of these patients to respond to infections, as IL-22 has anti-microbial properties." (PMID 28174512, 2017). "IL-17 and IL-22 are secreted by Th17 cells, promote neutrophils recruiting and prevents pathogens from disseminating, as well as stimulate epithelial proliferation and protects the intestinal barrier function during infection." (PMID 29029438, 2017). "Interestingly, rIL-22 administration prior to infection tended to decrease MIP-2 expression in the lungs of infected mice compared with PBS-treated mice (p = 0.17) in contrast with IL-22 neutralisation which led to an increase of CXCL2 expression." (PMID 28887540, 2017). "IL-22 has been reported to have an essential ability in recruiting neutrophils and soluble antibacterial factors to aid the response against bacterial infection, such as infection by N. gonorrhoeae and Citrobacter rodentium." (PMID 28899359, 2017). "Indeed, besides Th17 cells, an increased presence of ILC3 positive for intracellular IL-22 were seen in the whole course of infection of IDO1−/− mice." (PMID 28791025, 2017). "We found that IL-22 protein level in the liver reached a peak at 3 days post infection (dpi)." (PMID 28634408, 2017). "Therefore, it is likely that the pro-inflammatory condition sustained by IL-22 is protective against infection, promoting the longevity of these subjects." (PMID 28174512, 2017). "Surprisingly, the production of TNFα, IL-17, and IL-22 were moderately elevated from the splenocytes of knockout mice, particularly at day 3 postinfection, while mostly leveling up during the late course of infection." (PMID 27046240, 2016). "Furthermore, at an early time point of infection T cells from PbA-infected Il22−/− mice showed an enhanced IFNγ but a diminished IL-17 production." (PMID 27311945, 2016). "The reason, why IL-22−/− mice exhibited an increased body weight loss during infection, but not an increased pathology in compensation to wild-type mice is unclear." (PMID 27650379, 2016). "During infection, IL-22 is secreted by CD4-positive cells in an IL-23-dependent fashion." (PMID 27650379, 2016).
infection (continued). "In contrast, M28 GAS elicited significant cytokine increases in TNF-α, IL-17A, IL-6, IL-1β, and IL-22, as early as 3 to 7 days post-infection in the estradiol pulse model, and a significant cellular infiltrate in the lumen was observed in colonized WT mice compared to non-infected or IL-17A−/− mice." (PMID 27241677, 2016). "Furthermore, macrophages from IL-22−/− mice exhibited an unaltered MHCII expression in comparison to wild-type macrophages during infection." (PMID 27650379, 2016). "Dysregulation of IL-22 expression can occur in human diseases and in preclinical models, e.g. the crucial role of IL-22 in regulating homeostasis of epithelial cells at barrier surfaces has been identified in a mouse model infection." (PMID 27652524, 2016). "Moreover, dendritic cells from Il22−/− mice expressed a higher amount of the costimulatory ligand CD86 upon infection." (PMID 27311945, 2016). "IL-22 expression is highly increased in the intestine after infection with Clostridium difficile." (PMID 27424033, 2016). "The role of IL-22 following infection is equally diverse, where it has been shown to protect mice from infection with Citrobacter rodentium and Salmonella enterica, but appears not to affect the outcome of infection with Mycobacterium avium; susceptibility to Salmonella has been reported." (PMID 27055194, 2016). "Similarly IL-22 was found to protect against superimposed infection with S. pneumoniae following respiratory influenza A infection." (PMID 27375092, 2016). "However, IL-22 also elicits an inflammatory response in inflamed intestines as a result of infection with enteropathogenic bacteria." (PMID 27424033, 2016). "Hence this led to a significant increase in the recovery of proliferating OT1 T cells in Il22−/− recipient mice after infection with PbA-OVA on d5 p.i.." (PMID 27311945, 2016). "Additionally, we observed increased levels of IL-22 in the sera of C57BL/6 mice after 14 days of infection." (PMID 27650379, 2016). "Strikingly, expression of regulatory factors (IL-10, IL-25, Foxp3), which arise following H. diminuta infection, were either enhanced or sustained in IL-22-/- mice, uncovering a novel role for IL-22 as a brake for these regulatory events following infection with this parasitic helminth." (PMID 27055194, 2016). "γδ T-cells were increased two months after infection in IL-17RA-deficient mice, but not in IL-22- or double IL-17RA-IL-22-deficient mice, as compared to wild-type mice." (PMID 27853279, 2016). "However, as we observed an induction of Il22 mRNA expression in the heart during infection, we also analyzed acute heart pathology." (PMID 27650379, 2016). "Similar to cells from mice, PBMCs from infected patients, but not healthy subjects, produced IL-22 in response to stimulation with leishmanial antigen, suggesting that IL-22 may be important in human patients as well as in experimental murine infections." (PMID 26285207, 2015). "Since IL-22 can have tissue protective effects, we investigated whether IL-22 might help control pathology during infection with leishmania." (PMID 26285207, 2015). "Therefore, we analyzed the expression of several genes at the peak of infection to assess keratinocyte functions in the lesions of wild-type and Il22-/- mice." (PMID 26285207, 2015). "Since the IL-17/IL-22 pathway has also been shown to promote neutrophil recruitment into infected tissues, and some CARD9-deficient patients have reduced Th17 cells in the peripheral blood, we determined the levels of IL-17 and IL-22 in the brains of WT and Card9-/- mice following infection." (PMID 26679537, 2015). "Interestingly, gene transcript and protein analysis revealed significantly impaired (P < 0.05) induction of IL-22 in Retnlb-/- mice during infection as compared to C57BL/6 mice." (PMID 26285214, 2015). "IL-22 signaling is protective in multiple models of infection and elicits antimicrobial peptides as well as protective cytokine responses in the setting of infection." (PMID 26171402, 2015).
infection (continued). "Future studies are warranted to determine whether IL-22 directly or indirectly participates in the maintenance of the GI tract lymphoid tissue and host defense against pathogens in the presence of an infection." (PMID 26793707, 2015). "We infected wild-type and Il22-/- mice with L. braziliensis and followed the course of infection." (PMID 26285207, 2015). "The up-regulation of IFNγ and IL22 during the infection may participate in the clearance of the infection and the recovery of the epithelial integrity, respectively." (PMID 25890354, 2015). "However, in a model of infection with Mycobacterium tuberculosis, the IL-22 cells are dependent on IL-23 and the majority of the IL-22-producing T cells also express IFNγ." (PMID 25253467, 2014). "Indeed, epithelial cells responded early to mycobacterial infection by secreting IL-6 and the anti-inflammatory IL-22, while the anti-inflammatory IL-10 increased two days after infection." (PMID 24489729, 2014). "The swift expansion of a PA-specific Th22 memory cell population would thus ensure a rapid production of an IL-22 producing cell that could migrate to the site of infection to mediate host defence and/or contribute to tissue repair." (PMID 24587305, 2014). "The balance between the protective and harmful effects of Th17 cells through cytokines IL17 and IL22 is extremely delicate and there are reports supporting their contribution to host defence and others highlighting their inflammatory damage when the infection persists over time." (PMID 25526753, 2014). "After αIL-22 treatment, however, virus was detected in eight of ten lungs, seven of which demonstrated higher virus load than IgG-treated mice, highlighting an antiviral function for IL-22 during initial infection and suggesting it sets a threshold for acute virus replication in the lung." (PMID 24721575, 2014). "This may reflect higher IL-22 turnover upon infection due to increased IL-22R expression and/or possible secretion of IL-22 binding protein that, after depletion of IL-22+ cells, reduced detectable soluble IL-22 below levels measured in naive tissue." (PMID 24721575, 2014). "Additionally, in a murine model of gut inflammation following infection with Citrobacter rodentium, IL-22 plays an important role in host defence." (PMID 24587305, 2014). "However, it is critical to have a “guardian”, in this case IL-22, to prevent overproduction of CCL20 during the late phase of infection leading to tissue damages caused by amplified inflammatory responses." (PMID 24824519, 2014). "More specifically, ILC3s have been shown to be a dominant innate source of IL-22 during infection." (PMID 24586147, 2014). "IL-22 is a Th17 cytokine that induces a series of anti-microbial peptides upon infection." (PMID 24068935, 2013). "infections, in which R. variabilis may establish infection in otherwise healthy people through avoiding induction of IL-22." (PMID 23798999, 2013). "Consequently, IL-22−/− mice were capable to efficiently control mycobacterial growth after low dose infection with a similar survival kinetic than infected C57BL/6 mice." (PMID 23460846, 2013). "The increased resistance seen later in infection in IL-22-deficient but not IDO1-deficient mice, prompted us to define mechanisms of resistance that are independent from IL-22 but dependent on IDO1." (PMID 23853597, 2013). "Like IL-17A, IL-22 is expressed early after infection with Mtb in an IL-23-dependent manner." (PMID 23460846, 2013). "However, significant differences between C57BL/6 and IL-22−/− mice were only seen at d43 and d219 of infection with reduced numbers of naive CD4+ T cells and increased amounts of central memory T cells in mutant mice, respectively." (PMID 23460846, 2013). "Earlier during infection (d21), only lungs of IL-22−/− mice could worse with Mtb infection than C57BL/6 mice showing slightly higher (∼0.6 log10) bacterial loads." (PMID 23460846, 2013).
infection (continued). "Interestingly, IL-22 transcription increased post-infection in the unvaccinated calves, as we have previously shown; a pattern that was mirrored in the BCG vaccinated animals." (PMID 23300440, 2012). "We conclude that HIV exposure without infection was associated with blunted IL17/IL22 and pro-inflammatory responses, both systemically and at the site of mucosal HIV exposure." (PMID 22928014, 2012). "Infection with avirulent S. flexneri led to a substantial upregulation of only IL-22 (3.3 fold), although upregulation (1.4 fold) could also be detected for IL-17F and TNF-α." (PMID 22675469, 2012). "To determine whether the microbial induction of IL-22 expression prior to infection was important to the observed protection against C. rodentium infection we used immunoneutralization of IL-22." (PMID 22046427, 2011). "Therefore, LM infection induces the production of IL-22, and the production of IL-22 is dependent on IL-23 during a primary systemic i.v. infection." (PMID 21347242, 2011). "By day 4 p.i., 8/9 B6 and 9/9 IL-22 KO mice had succumbed to the infection." (PMID 21347242, 2011). "Furthermore, TLR signaling through MyD88-dependent, IL-1R- and IL-22-dependent signaling pathways confines infection to the mucosal surface and prevents bacteremia." (PMID 22046427, 2011). "Furthermore, only IL-22 showed transcriptional differences depending on embryonic age at the time of infection." (PMID 21603634, 2011). "IL-22 has similar effects to IL-17 on ECs but has been suggested to control yeast cell growth, as well as controlling epithelial layer integrity during infection, thus helping to control cell numbers and invasion of the epithelium during an infection event." (PMID 21776285, 2011). "Importantly, our data now show that IL-22 is dispensable for clearance of LM at days 5 and 7 p.i., as well as during secondary infection." (PMID 21347242, 2011). "Differentiation, distribution and immune regulation of human IL-22-producing T cells in infections remain unknown." (PMID 20195465, 2010). "In fact, development, function and immune regulation of human IL-22-producing T cells in infections remain largely unknown." (PMID 20195465, 2010). "However, many other cytokines can do so, too and multiple signals, including IL-22 and IFNγ, will drive tissue inflammation in a redundant fashion during the course of a real infection." (PMID 21124903, 2010). "Similarly, significant increases in numbers of IL-22 producing T cells were also detected in bronchoalveolar lavage fluids (BALF) during the infection." (PMID 20195465, 2010). "Spontaneous, basal IL-22 secretion and ileal IL-22 induction post-infection are also worth noting." (PMID 21085698, 2010). "Although RorcΔ369 mice exhibited defects in total ILC3s, IL-17-producing, and IL-22-producing ILC3s in the colon after infection, IL-17-producing CD4+ T cells were significantly increased in RorcΔ369 mice, which may compensate for host defense against C. rodentium in RorcΔ369 mice." (PMID 40766221, 2025). "At the same time, the data show that in the process of Chlamydia respiratory infection, IL-22 is the key cytokine that determines the growth and proliferation of various T-cell subsets, such as Th17 cells, especially early in the infection, which may also involve γδT cells, NKT cells, and others." (PMID 41156830, 2025). "Under conditions such as impaired intestinal barrier function, infection, and inflammation, IL-22 can exert beneficial repair and defensive effects; however, in certain chronic inflammatory conditions and tumorigenesis, IL-22 may exacerbate the disease or promote tumor growth." (PMID 41019044, 2025). "Indeed, anti-inflammatory genes exhibited a considerable presence in the infection setting; the IL-10 family of genes important for wound healing and repair (IL1r2, IL1r1, IL-24, IL-19, IL-22) were elevated >2- to 60-fold, although IL-10 itself remained unchanged." (PMID 40586608, 2025).
infection (continued). "Since transporter expression was not directly induced by IL-22, we investigated whether the loss was due to infection-induced changes in IEC subpopulations." (PMID 41361166, 2025). "However, consistent with the previous reports and our results of the comparable burden of Citrobacter rodentium in the early infection phase, the proportions of IL-22+ CD4+ T cells and IL-22+ ILC3 were maintained at an equal level in cLPs of water-restricted mice." (PMID 38799550, 2024). "Thus, despite indications of the role of IL-22 in the immunomodulation of C. deuterogattii infection in mice, further studies are needed to more clearly elucidate the immunopathological impacts of this infection in human hosts." (PMID 39635124, 2024). "We also assessed whether Nlrp6 impacted infection-induced IL-18 and IL-22 release." (PMID 39428744, 2024). "Notably, the genes induced by the infection were enriched in multiple immune activation pathways, including cytokine-cytokine receptor interaction (e.g., Il22, Tnfrsf9 and Clcf1), JAK-STAT signaling pathway (e.g., Stat3), and chemokine signaling pathway (e.g., Ccr7) 33–35." (PMID 39013884, 2024). "However, we found a critical role for T cell-derived IL-22 in programming DCCs to accelerate their transition to pro-senescence during infection, and the migration of maturing DCC subsets in infected Il22∆Tcell mice was irregular, suggesting discontinuous terminal differentiation." (PMID 38600382, 2024). "Thus, the increased permeability that we detected with 4-kD FITC-dextran at Day 12 of post-infection in Il22−/− mice may be due to the leak and/or unrestricted pathways, although the apparent tissue damage suggests the unrestricted pathway." (PMID 38557196, 2024). "Interestingly, IL-22 plays a role in maintaining the Th2 profile during R265 infection." (PMID 39635124, 2024). "Hence, during the early phase of infection, IL-22 can unidirectionally upregulate IL-18 levels at the primary site of infection, allowing IL-18 to promote goblet cell maturation and subsequent mucin secretion, potentially to help flush S. Typhimurium down the GI tract." (PMID 39428744, 2024). "The pivotal role of IL-22 in the containment of cryptococci and its effectiveness in preventing lung damage, underscore the critical importance of immune regulation during fungal lung infections, and emphasizes the role of IL-22 regulatory properties during this infection." (PMID 39635124, 2024). "Moreover, it has been proposed that due to the compensatory effect of other cytokines, IL-22 deficiency does not affect the susceptibility of mice to H. pylori or their mortality after infection, which contradicts the previous conclusion." (PMID 36839448, 2023). "Salmonella typhimurium selectively enhanced ILC3s to produce IL-22 which could promote infection." (PMID 37304260, 2023). "APECED patients feature selective infection susceptibility to CMC with a frequency of ~80-90%, associated with serum autoantibodies against IL-17F (frequency, ~20-85% depending on the cohort), IL-17A (frequency, ~35%), and IL-22 (frequency, ~70-90% depending on the cohort)." (PMID 34964702, 2022). "Thus, it would be interesting to know what cells might be involved in the production of IL-22 during the infection, and more so if IL-22 is somewhat produced in the same manner or maybe regulated differently with IL-17A during R. anatipestifer infection." (PMID 34805416, 2021). "Indeed, infections of 2D mouse Ileum organoids with the mouse corona virus (MHV) could be reduced with an IL22 pretreatment." (PMID 34045640, 2021). "IL-22 belongs to the IL-10 cytokine family and is produced in the intestinal mucosa by group 3 innate lymphoid cells (ILC3s; produces IL-22 during the early stage of infection) and CD4 + T cells (including Th17 cells and Th22 cells; produces IL-22 during late stage of infection)." (PMID 32082288, 2020). "Therefore, CD4+ cells are the main source of IL-22 in the late phase of infection." (PMID 32887435, 2020).